PTK6 (protein tyrosine kinase 6)
Diseases named in the same sentence as PTK6 in open-access papers (continued):
Sharing a sentence is not in itself a finding about the gene and the disease.
melanoma (5 papers, 2014 to 2025). A malignant, usually aggressive tumor composed of atypical, neoplastic melanocytes. "This study further confirmed through functional experiments that mutations at this site would lead to the loss of PTK6 function and significantly inhibit the proliferation and invasion ability of melanoma cells." (PMID 40809015, 2025). "We obtained the risk scores of patients with melanoma: risk score = (−0.379123977 × expression of IFNG) + (−0.662084468 × expression of DAPK2) + (0.342818269 × expression of ATG9B) + (0.406559238 × expression of PTK6) + (0.807218069 × expression of BIRC5) + (0.364523721 × expression of EGFR)." (PMID 36690663, 2023). "To explore additional genes potentially linked to PTK6, we integrated and examined a total of 472 cutaneous melanoma cases from TCGA-SKCM, 31 primary melanoma samples from GSE46517, and 46 primary melanoma samples from GSE15605." (PMID 40809015, 2025). "Three genes (CYP3A4, GBA2 and PTK6) were identified to besignificantly downregulated in melanoma patients." (PMID 40636215, 2025). "By establishing a novel prognostic gene signature, delineating PTK6’s regulatory network, and demonstrating its influence on melanoma cell proliferation and invasion, we identify PTK6 as a promising biomarker and potential therapeutic target for CM." (PMID 40809015, 2025). "Meanwhile, we also knocked down and overexpressed PTK6 in the melanoma cell line (A375), and tested the ability of A375 proliferation, migration, and invasion." (PMID 36690663, 2023). "Furthermore, experimental validation using melanoma cell lines revealed that PTK6 plays a regulatory role in cell proliferation, migration, and invasiveness." (PMID 40809015, 2025). "Our prior study identified a notable increase in PTK6 mRNA levels in melanoma samples." (PMID 40809015, 2025). "Therefore, we conclude thatgenes CYP3A4 and PTK6, which are modulated by diosgenin, are likely to be the major targets conferring S. nigrum theanti-melanoma effect." (PMID 40636215, 2025). "Subsequently, CCK-8 assays and colony formation assays revealed that cell proliferation in the si-PTK6 group was significantly reduced in both A875 and SK-MEL-28 cell lines compared to the control (ctrl) and si-NC groups, indicating that PTK6 plays a promotive role in melanoma cell proliferation." (PMID 40809015, 2025). "Future research should address these limitations by using larger and more diverse sample sets, expanding clinical and animal model experiments, conducting functional studies in additional melanoma cell lines, and exploring PTK6’s therapeutic potential and biological mechanisms." (PMID 40809015, 2025). "Despite being mentioned in a limited number of studies on melanoma, the association between PTK6 and cutaneous melanoma (CM) has not been investigated." (PMID 40809015, 2025). "Additionally, using PCR and Western blot (WB) analysis, we observed that PTK6 expression in four melanoma cell lines was markedly higher than in human epidermal melanocytes (HEMCs)." (PMID 40809015, 2025). "The data showed that PTK6 also promoted tumor growth in melanoma." (PMID 36690663, 2023). "Furthermore, according to the differential expression of PTK6 in melanoma patients, we divided the patients into a PTK6 high-expression group and a PTK6 low-expression group." (PMID 36690663, 2023). "Thus, the positive correlation between PTK6 and CD56bright NK cells may imply that PTK6 affects melanoma progression by modulating NK cell function or activity within the tumor microenvironment." (PMID 40809015, 2025). "The anti-melanoma effect of S. nigrum is likely through the modulation of three unique melanoma-related gene targets(CYP3A4, GBA2 and PTK6) by its two unique active ingredients (diosgenin and solanocapsine)." (PMID 40636215, 2025). "Our data show that three unique melanoma-related gene targets (CYP3A4, GBA2and PTK6) for two unique active ingredients (diosgenin and solanocapsine) present in S. nigrum have potential role." (PMID 40636215, 2025).
melanoma (continued). "Vemurafenib, an inhibitor of mutant BRAF used for the treatment of melanoma, also inhibits PTK6, but not SRC, at nanomolar concentrations." (PMID 36228719, 2022). "To further investigate the expression of PTK6 in SKCM, we initially compared the expression levels of PTK6 in tumor tissues and adjacent non-tumor tissues from melanoma patients using immunohistochemistry." (PMID 40809015, 2025).
endometrial cancer (4 papers, 2014 to 2026). Primary or metastatic malignant neoplasm involving the endometrium (mucous membrane that lines the endometrial cavity). "In the present study, we found that elevated PTK6 expression was associated with worse prognoses, suggesting that PTK6 might promote endometrial cancer progression by inhibiting autophagy." (PMID 33109128, 2020). "We constructed a prognostic model of endometrial cancer containing four risk ARGs (CDKN2A, PTK6, ERBB2, and BIRC5) using multivariate and univariate Cox, and LASSO regression analyses." (PMID 33109128, 2020). "In summary, by collecting and analyzing the transcript information of endometrial cancer samples from TCGA database, we identified four prognosis-associated autophagy genes (CDKN2A, PTK6, ERBB2, and BIRC5)." (PMID 33109128, 2020). "Immunohistochemistry revealed ISH scores for four risk kinases (ALPK2, TTK, PTK6, and CIT) were significantly higher in endometrial carcinoma tissues than in healthy endometrium, which suggested that high expression of these genes may contribute to the progression of UCEC." (PMID 36158685, 2022). "Immunohistochemistry revealed ISH scores for four risk ARGs (CDKN2A, ERBB2, PTK6, and BRIC5) were significantly higher in endometrial cancer tissue than in healthy endometrial tissue, which suggested that these genes are highly expressed in endometrial cancer tissues." (PMID 33109128, 2020). "Using univariate Cox regression and Least absolute shrinkage and selection operator (LASSO), seven kinases (ALPK2, CAMKV, TTK, PTK6, MAST1, CIT, and FAM198B) were identified to establish a prognostic model of endometrial cancer." (PMID 36158685, 2022). "Our prognostic model assessing four ARGs (CDKN2A, PTK6, ERBB2, and BIRC5) suggested their potential as independent predictive biomarkers and therapeutic targets for endometrial cancer." (PMID 33109128, 2020). "Four ARGs (CDKN2A, PTK6, ERBB2 and BIRC5) were selected to establish a prognostic model of endometrial cancer." (PMID 33109128, 2020). "Immunohistochemistry suggested that among the four ARGs the protein levels of CDKN2A, PTK6, ERBB2, and BIRC5 were higher in endometrial cancer than healthy endometrial tissue." (PMID 33109128, 2020). "For example, a chromosome 20q cluster comprising four genes (PTK6, SRMS, RTEL1, and PRPF6) were all amplified in uterine/endometrial cancers and lung adenocarcinomas." (PMID 24874471, 2014).
esophageal cancer (4 papers, 2013 to 2023). A primary or metastatic malignant neoplasm involving the esophagus. "A recent study on esophageal cancer reported that FSCN1 may function as an RBP; FSCN1 binding to the PTK6 mRNA precursor was found to inhibit PTK6 transcription." (PMID 38077434, 2023).
glioma (4 papers, 2017 to 2025). A benign or malignant brain and spinal cord tumor that arises from glial cells (astrocytes, oligodendrocytes, ependymal cells). "After constructing the risk model, we screened out the signature composed of five ATGs (BID, BAG1, PTK6, NRG3, MAP1LC3C) with the best prognosis prediction performance, indicating these five ATGs play an important role in glioma." (PMID 33768004, 2021).
lung carcinoma (4 papers, 2014 to 2024). "PTK6 expression was validated in vitro experiments (lung cancer cell lines PC9, NCI-H1975, and HCC827; human normal lung epithelial cells BEAS-2B)." (PMID 38573548, 2024). "Furthermore, following the inhibition of PTK6 overexpression, a reduction in cell viability and proliferation was observed in these lung cancer cell lines." (PMID 38573548, 2024). "Western blot (WB) revealed the PTK6 protein expression in lung cancer cell lines." (PMID 38573548, 2024). "Abberant overexpression of PTK6 has been described in other types of cancers and it has previously been suggested that PTK6 may be a useful biomarker to predict outcomes of patients with various cancers including breast, head and neck, ovarian and lung cancers." (PMID 24788754, 2014). "We show that erlotinib, an FDA-approved EGFR inhibitor for the treatment of lung cancer inhibits PTK6, AKT, and ERK1/2 in cells that overexpress active PTK6." (PMID 36228719, 2022).
nasopharyngeal carcinoma (4 papers, 2013 to 2023). A carcinoma arising from the nasopharyngeal epithelium. "The aim of this study was to analyze the expression of protein tyrosine kinase 6 (PTK6) in nasopharyngeal carcinoma (NPC) samples, and to identify whether PTK6 can serve as a biomarker for the diagnosis and prognosis of NPC." (PMID 23758975, 2013).
cervical cancer (3 papers, 2016 to 2023). A primary or metastatic malignant neoplasm involving the cervix. "Our study showed that PTK6 overexpression was associated with short survival for patients with cervical cancer." (PMID 27311570, 2016). "Overexpression of GAB1 was able to offset the inhibitory effects of PTK6 knockdown on cervical cancer cells." (PMID 36405012, 2022). "Cervical cancer cells were protected against the progression of malignant cervical cancer when PTK6 expression was knocked down." (PMID 36405012, 2022). "PTK6 expression levels were detected with IHC staining in 150 cervical cancer specimens and 10 normal cervical epithelia specimens." (PMID 27311570, 2016). "In our study, PTK6 was overexpressed in freshly frozen cervical squamous cell cancer specimens, and PTK6 protein was overexpressed in tumor tissues from 150 patients with cervical cancer." (PMID 27311570, 2016). "PTK6 expression is an independent prognostic predictor for cervical cancer." (PMID 27311570, 2016). "PTK6 expression may be an independent prognostic predictor of cervical cancer." (PMID 27311570, 2016). "For instance, it was observed that the expression levels of PTK6 and GAB1 were much higher in cervical cancer cell lines compared to those noted in normal cervical epithelial cells." (PMID 36405012, 2022). "Thus, our data suggest that PTK6 may be used as a prognostic factor for cervical cancer." (PMID 27311570, 2016). "The absence of protein tyrosine kinase 6 (PTK6) expression reduces the proliferative capacity of cervical cancer cells and apoptosis induction in a GAB1-dependent manner." (PMID 37627207, 2023).
gastric cancer (3 papers, 2016 to 2025). A primary or metastatic malignant neoplasm involving the stomach. "The aberrant expression of PTK6 has been identified in multiple malignant tumors including breast, colon, head and neck, ovary, prostate, lung, bladder, bile duct, pancreas, and gastric cancer, as well as T- and B-cell lymphoma." (PMID 34551797, 2021). "To test if PTK6 phosphorylates parafibromin, we co-expressed PTK6 and parafibromin in AGS human gastric cancer cells." (PMID 27650679, 2016).
head and neck cancer (3 papers, 2013 to 2020). A primary or metastatic malignant neoplasm affecting the head and neck. "In head and neck cancer, the high-risk genes are associated with PTK6 signaling (p value = 0.01), which regulates cell cycle and growth, and cytokines and inflammatory response (p value = 0.009)." (PMID 33311484, 2020). "The overexpression of tyrosine kinases (including EphA1, PTK6/BRK, and Ron) were reported in head and neck cancers which included pharyngeal, hypopharyngeal, tonsilar, supraglottic and some oral cancers." (PMID 23497344, 2013).
invasive ductal carcinomas (3 papers, 2014 to 2022). "Active PTK6 appeared to correlate with grade of tumor; in low-grade ductal carcinomas, the P-Y342 signal was low to undetectable, but in the high-grade invasive ductal carcinomas, a strong P-Y342 PTK6 signal was detected at the membrane of tumors cells that had breached the basement membrane." (PMID 25153721, 2014). "Breast tumor kinase (BRK, also known as protein tyrosine kinase 6), which is related to the Src family of tyrosine kinases, is overexpressed in approximately 85% of invasive ductal carcinomas." (PMID 36010693, 2022).
lung adenocarcinoma (3 papers, 2014 to 2025). A carcinoma that arises from the lung and is characterized by the presence of malignant glandular epithelial cells. "The Wilcoxon rank-sum test revealed that PTK6 is significantly overexpressed in 17 out of 33 cancer types, notably in bladder, breast, and lung adenocarcinoma, compared to normal tissues." (PMID 40809015, 2025). "The aim of this study was to identify PTK6 as a novel prognostic biomarker in pan-cancer, especially in lung adenocarcinoma (LUAD), which is correlated with immune infiltration, and to clarify its clinicopathological and prognostic significance." (PMID 38573548, 2024).
lymph node metastasis (3 papers, 2013 to 2023). "The incidence of PTK6 expression in the LNM + group was 78.4% and in the LNM-group it was 28.0% (P < 0.05), suggesting that PTK6 protein expression may be related to lymph node metastasis." (PMID 37932734, 2023). "Additionally, the RRs (relative risks) showed that high PTK6 expression had lower risk than low PTK6 expression, and that no cervical lymph node metastasis had lower risk than lymph node metastasis." (PMID 23497344, 2013). "Perhaps the status of lymph node metastasis in patients with TNBC can affect the effect of PTK6 on the prognosis, or perhaps PTK6 is only negatively correlated with the prognosis of patients with metastatic TNBC." (PMID 37932734, 2023).
oral squamous cell carcinoma (3 papers, 2013 to 2023). "Previous research investigated the expression of PTK6 in human oral squamous cell carcinomas and normal oral epithelium (NOE)." (PMID 35562900, 2022).
uveal melanoma (3 papers, 2023 to 2025). A melanoma derived from melanocytes of the uveal tract. "A prior investigation on uveal melanoma proposed that PTK6 potentially enhances the proliferation, migration, and invasion of uveal melanoma cells by suppressing autophagy." (PMID 40809015, 2025). "A very recent study on uveal melanoma cells demonstrates that overexpression of SOCS3 can partially inhibit the PTK6-driven uveal melanoma cell proliferation." (PMID 37509364, 2023). "This indicated that SOCS3 was involved in the autophagy of PTK6 in uveal melanoma." (PMID 36690663, 2023).
asthma (2 papers, 2020 to 2022). "PTK6 is identified as a genetic susceptibility molecule for severe asthma." (PMID 35619697, 2022). "The combined interaction scores resulted in higher interactions for the genes STAT3, AGO2, COL1A1, CLCN6, and KSR for moderate asthma and JAK2, INSR, ERBB2, NR3C1, and PTK6 for severe asthma." (PMID 32512817, 2020). "For example, in severe asthma, the combined interaction scores for the STAT3, AGO2, COL1A1, CLCN6, and KSR1 genes yielded a higher interaction for the moderate asthma phenotype, and the JAK2, INSR, ERBB2, NR3C1, and PTK6 genes were more interactive for the severe asthma phenotype." (PMID 32512817, 2020).
cervical squamous cell carcinoma (2 papers, 2016 to 2025). A squamous cell carcinoma arising from the cervical epithelium. "In conclusion, we demonstrated that PTK6 was overexpressed in cervical squamous cell cancer and that high PTK6 expression was associated with short OS." (PMID 27311570, 2016). "Our data indicated that both PTK6 mRNA and protein levels were elevated in cervical squamous cell cancer and the elevated cytoplasmic expression of PTK6 was associated with tumor grade and short patient survival." (PMID 27311570, 2016). "In our study, we detected PTK6 expression in early-stage cervical squamous cell cancer and analyzed the relationship between PTK6 expression and patients’ clinicopathologic characteristics." (PMID 27311570, 2016). "Multivariate Cox regression analysis showed that the expression level of PTK6 in cervical squamous cell cancer was an independent prognostic factor for patient survival (hazard ratio = 5.999, 95% confidence interval 1.622–22.191, P < 0.05)." (PMID 27311570, 2016). "This study aimed to investigate the expression level and clinical significance of PTK6 in early-stage cervical squamous cell cancer." (PMID 27311570, 2016). "The expression of PTK6 was detected using immunohistochemical staining in 150 formalin-fixed, paraffin-embedded, early-stage cervical squamous cell cancer sections and 10 normal cervical tissue sections." (PMID 27311570, 2016). "In this study, we investigated the expression level and clinical significance of PTK6 in early-stage cervical squamous cell cancer." (PMID 27311570, 2016). "Furthermore, our results suggest that the PTK6 expression is an unfavorable independent prognostic factor in patients with early-stage cervical squamous cell cancer." (PMID 27311570, 2016). "However, PTK6 expression status and its role in cervical squamous cell cancer are unknown." (PMID 27311570, 2016). "The expression level of PTK6 and its clinical relevance in cervical squamous cell cancer have not been studied." (PMID 27311570, 2016). "Immunohistochemical analysis showed that PTK6 was not expressed in normal cervical tissues but was overexpressed in the cytoplasm of cervical squamous cell cancer cells." (PMID 27311570, 2016). "Quantitative reverse transcription-polymerase chain reaction (qRT-PCR) and western blotting analysis were performed to detect PTK6 mRNA and protein expression levels in 10 freshly frozen, early-stage cervical squamous cell cancer specimens and adjacent non-tumorous cervical tissues." (PMID 27311570, 2016).
liver cancer (2 papers, 2011 to 2025). An epithelial or non-epithelial malignant neoplasm that arises from the liver. "Remarkably, Reactome enrichment analysis suggested that genes pertaining to PTK6 expression and the regulation of HMOX1 expression and activity could represent one of the mechanisms through which metformin acts in the treatment of liver cancer." (PMID 40583627, 2025). "The HepG2 liver cancer cell line does not express PTK6 and is a negative control." (PMID 21479203, 2011).
metastatic disease (2 papers, 2019 to 2020). "Moreover, immunohistochemistry (IHC) staining of primary and metastatic tumors showed that PTK6 reversed the effects of PSPC1 on downregulating E-cadherin and upregulating vimentin, β-catenin, c-Myc and Wnt3a." (PMID 31844057, 2019).
ovarian tumor (2 papers, 2010 to 2013). "PTK6 was also considered an attractive candidate for further study because it is highly expressed in multiple tumor types, including breast and ovarian tumors." (PMID 20668531, 2010). "The rather restricted expression of PTK6 in normal tissues and the prevalence of PTK6 copy number gain and high expression in some breast and ovarian tumors improve the chance of selectively targeting malignant cells." (PMID 20668531, 2010). "PTK6 is expressed in multiple human tumor types, including breast and ovarian tumors." (PMID 20668531, 2010).
pancreatic adenocarcinoma (2 papers, 2014 to 2025). "PTK6 expression was also observed in human pancreatic adenocarcinomas." (PMID 24788754, 2014). "Notably, PTK6 emerged as a detrimental factor in Adrenocortical carcinoma (ACC), Pancreatic adenocarcinoma (PAAD), Mesothelioma (MESO), Acute Myeloid Leukemia (LAML), Kidney renal clear cell carcinoma (KIRC), and Skin Cutaneous Melanoma (SKCM)." (PMID 40809015, 2025).